LINC02691 (long independently transcribed non-coding RNA 2691)
Synonyms: C14orf144
Gene: Long non-coding RNA gene on chromosome 14 (104,223,496 to 104,315,671, forward strand). Ensembl gene ENSG00000258913.
Diseases named in the same sentence as LINC02691 in open-access papers:
LINC02691 is named in the same sentence as 1 disease in open-access papers, as found by Europe PMC text mining. Sharing a sentence is not in itself a finding about the gene and the disease. The quoted sentences say what the papers report.
liver cancer (1 paper, 2021). An epithelial or non-epithelial malignant neoplasm that arises from the liver. "As further verification of this finding, the difference in LINC02691, LINC02499, LINC01354, and NAV2-AS4 expression in liver cancer tissues (n = 371) was statistically significant (p < 0.05) compared with normal liver tissues (n = 50)." (PMID 34141458, 2021).